EZH2 (enhancer of zeste 2 polycomb repressive complex 2 subunit)
Diseases named in the same sentence as EZH2 in open-access papers (continued):
Sharing a sentence is not in itself a finding about the gene and the disease.
tumor (continued). "The analysis of mitotic cell populations revealed a significant increase in the percentage of EZH2-positive mitotic cells in tumor tissues compared to benign controls." (PMID 40766612, 2025). "It has been previously demonstrated to inhibit the progression of EC by disrupting the interaction between HOTAIR and EZH2, thus restoring the expression of multiple tumor suppressor genes." (PMID 41353219, 2025). "K27M sequesters PRC2, depleting global H3K27me3 while hyperactivating EZH2 locally, silencing tumour suppressors and promoting stemness, with a stronger impact in H3.3 contexts." (PMID 40987316, 2025). "Higher expression levels of Ezh2 and Suz12 are strongly correlated with tumour progression and overall survival." (PMID 40182023, 2025). "GBM cells exploit HDACs to reduce DNA damage from radiation and use EZH2 to maintain stemness and suppress tumor suppressors." (PMID 41234540, 2025). "The goal of EZH2 inhibitor drugs is to break tumor‐suppressor gene silencing which leads to cancer cell death and prevents their proliferation." (PMID 40959208, 2025). "As EZH2 acts as an epigenetic silencer via its function of regulating H3K27me3, it plays an important role in tumorigenesis and tumor progression." (PMID 39850359, 2025). "EZH2 expression depends on clinical parameters such as age, tumor and lymphatic invasion, TNM and metastasis in all tumors, with differences within subtypes." (PMID 40868070, 2025). "While our data indicate significant changes in immune cellularity, immune-related gene expression, and epigenetic modulation following EZH2 suppression, the role of tumor-immune interactions remains unresolved." (PMID 39946195, 2025). "While EZH2 is widely recognized as a driver of tumor progression and poor prognosis, its role as a tumor suppressor in specific cancer types also warrants attention." (PMID 40042761, 2025). "In parallel, frequent mutations in chromatin modifiers (e.g., KDM6A, KMT2D) and overexpression of histone-modifying enzymes (e.g., EZH2) alter the tumor epigenome to promote immune evasion and tumor aggressiveness." (PMID 40918525, 2025). "The expression of EZH2 in melanoma cells is reported to be also regulated by other two different tumor suppressor lncRNAs, i.e., LINC-PINT and by GAS5, but using different strategies." (PMID 40282449, 2025). "The small-molecule inhibitor SHR2554, which targets EZH2, demonstrated significant anti-tumor effects on various TCL cell lines." (PMID 40659662, 2025). "On the contrary, decreased expression of epithelial markers and increased expression of mesenchymal markers were observed in EZH2 overexpressing cells, thereby promoting the spread of tumor cells." (PMID 39944625, 2025). "EZH2 is a master regulator of NE lineage plasticity in PC and has been associated with the methylation and silencing of PTEN in various tumor types." (PMID 40650023, 2025). "The significant overlap highlights the dual roles of genes such as TOP2A, CCNB2, BUB1, TPX2, and EZH2 in both tumor initiation and tumor progression, reinforcing their potential as key biomarkers for PCa." (PMID 40626556, 2025). "This FDA-approved EZH2 inhibitor has shown efficacy in advanced epithelioid sarcoma and follicular lymphoma and has demonstrated anti-tumor activity in HCC by inhibiting CD13 and β-catenin expression, thus curtailing tumor development and progression." (PMID 40057667, 2025). "The lncRNA HOTAIR, implicated in various cancers including OSCC, suppresses the expression of downstream tumor suppressor genes by recruiting EZH2 and mediating H3K27 trimethylation." (PMID 41221298, 2025).
tumor (continued). "Numerous in vitro studies have demonstrated that inhibiting EZH2 can reverse these silencing effects, thereby restoring the activity of tumor suppressor genes and inhibiting tumor growth and progression." (PMID 40904706, 2025). "Additional driver alterations are necessary for the appearance of a tumor and 90% of patients with FL have certain mutations in genes regulating transcription and chromatin remodeling such as CREBBP, EP300, KMT2D and EZH2." (PMID 40725159, 2025). "Our study demonstrates that TPA and mezerein significantly induce transformed foci formation and proliferation in Bhas42 cells through the epigenetic regulation of Hmga2 and Ezh2, suggesting their role in tumour progression." (PMID 40182023, 2025). "SFN inhibits PcG proteins like Bmi1 and EZH2, reducing H3K27me3 levels, and thus blocking tumor progression." (PMID 40760406, 2025). "Overexpression of EZH2 correlates with the silencing of specific genes involved in tumor suppression and cellular differentiation." (PMID 40959208, 2025). "Recurrent mutations in key epigenetic regulators such as EZH2, KMT2D, CREBBP, and TET2 lead to altered chromatin states, repression of tumor suppressor genes, and enhanced oncogenic signaling." (PMID 40943058, 2025). "EZH2 inhibition disrupts immune evasion through multiple mechanisms, restores the tumor-immune cycle, and enhances the efficacy of immune checkpoint inhibitors." (PMID 41326356, 2025). "The pharmacological inhibition of EZH2 using compounds such as 3-Deazaneplanocin A reproduces these effects and suppresses tumor growth in vivo." (PMID 40508013, 2025). "Studies have indicated that Capsanthin can reduce the expression of critical proteins involved in tumor development, such as EZH2." (PMID 40038276, 2025). "EZH2 is often deregulated in ERMS and various other tumors, and in some cases, it is linked to increased tumor malignancy." (PMID 40076599, 2025). "And the effect of SETD2 or EZH2 on tumor microenvironment, especially tumor immune microenvironment needs to de deeply studied." (PMID 40959108, 2025). "It inhibits both mutant and wild-type EZH2, thereby reversing gene repression mediated by H3K27me3 and suppressing tumor proliferation." (PMID 40872531, 2025). "Using single-nuclear RNA sequencing (snRNA-seq), we identified a proliferative, hepatocyte-derived tumor cell population (cycling HepT) enriched for Enhancer of Zeste Homolog 2 (EZH2) expression, particularly in the aggressive embryonal subtype." (PMID 40766612, 2025). "Analysis of clinical tumor samples demonstrated that elevated EZH2 expression correlated significantly with advanced disease stages and reduced patient survival." (PMID 41209556, 2025). "In terms of mechanism, EZH2 inhibition has now been shown to more directly enhance tumor immunogenicity." (PMID 41335282, 2025). "EZH2 exhibits opposing functions: acting as a tumor suppressor during leukaemic initiation while serving as an oncogenic driver in AML maintenance." (PMID 40651916, 2025). "These tumor cell‐intrinsic events caused by squamocin provoked ER stress and the UPR, leading to ERAD‐mediated degradation of EZH2 and MYC, as well as apoptosis." (PMID 39823459, 2025). "EZH2 was overexpressed in HCC and was associated with advanced tumor stage, poor prognosis, Th2 and dendritic cell infiltration, and promoter hypermethylation." (PMID 41298718, 2025). "EZH2‐mediated histone methylation acts as a fundamental mechanism to silence tumor‐suppressor genes epigenetically." (PMID 40959208, 2025). "PI3K/AKT/mTOR inhibitors (e.g., everolimus, paxalisib) suppress tumor growth, while epigenetic modulators (EZH2, BET inhibitors) enhance immune recognition." (PMID 40223940, 2025). "MALAT1 can interact with the histone methyltransferase EZH2, leading to the enrichment of EZH2 in certain tumor suppressor gene promoter regions and catalyzing the trimethylation of H3K27me3." (PMID 41394878, 2025).
tumor (continued). "Our methylation analyses pinpointed two specific CpG sites within the EZH2 gene, cg08558971 and cg18416251, which exhibited inverse methylation patterns between tumor stages." (PMID 41209556, 2025). "AQB has shown therapeutic promise in endometrial cancer by suppressing tumor cell proliferation and the cell cycle, especially when combined with the EZH2 inhibitor tazemetostat." (PMID 40042761, 2025). "Our group previously demonstrated enhanced efficacy in activating anti-tumor transcriptional programs when combining DNMTi with EZH2-specific inhibition." (PMID 41000734, 2025). "The H3K27 methyltransferase EZH2 is also involved in the acquisition of cisplatin and CBPt resistance by silencing tumor suppressor genes." (PMID 41353219, 2025). "We found that a brief exposure to EVs derived from EZH2 inhibitor-treated cells skewed naïve neutrophils toward a pro-tumor phenotype characterized by high levels of PD-L1 and MSLN (Mesothelin) expression on the surface." (PMID 41226368, 2025). "In the PVT1-EZH2 axis, PVT1 stabilizes EZH2 protein levels and suppresses the expression of the miR-200 family of microRNAs and tumor suppressor genes, inducing an immunosuppressive phenotype." (PMID 41394878, 2025). "Consistently, EZH2-high tumours in our cohort exhibit an IL-1β/RORC-dominated Th17 signature that likely fosters tumour progression." (PMID 41209556, 2025). "Studies have demonstrated that MALAT1 binds to EZH2 55 and plays a crucial role in recruiting EZH2 to tumor suppressor gene loci, thereby facilitating PCa cell migration and invasion." (PMID 40959108, 2025). "The normal development and cellular function depend on EZH2 but its dysregulation leads to cancer formation through gene repression which blocks tumor inhibition." (PMID 40959208, 2025). "EZH2 expression, influenced by hypoxia-inducible factorα binding to hypoxia-responsive elements and promoter regions, plays a key role in tumor cell angiogenesis, metastasis, and invasion." (PMID 40042761, 2025). "As a result, EZH2 inhibitors represent a potential breakthrough strategy to enhance the efficacy of ICI-based immunotherapy by reshaping the characteristics of the tumor microenvironment towards a pro-immunogenic phenotype." (PMID 40554927, 2025). "Collectively, these results indicate that USP22 is a de novo interacting partner of EZH2 in tumor cells." (PMID 41252204, 2025). "EZH2 inhibits genes responsible for suppressing carcinogenesis, and inhibition of EZH2 activity can reduce tumor growth." (PMID 40725030, 2025). "In a mouse model study, BAP loss resulted in an increase in EZH2 and PCR2, and BAP1 loss cells were sensitive to EZH2 inhibition, providing evidence for the potential role of BAP1 in mediating tumor sensitivity of EZH2 inhibition." (PMID 40361508, 2025). "EZH2 catalyzes H3K27me3, repressing pro-inflammatory and anti-tumor genes in TANs; therefore, EZH2 inhibition can restore neutrophil-mediated tumor cytotoxicity." (PMID 40299416, 2025). "Dysregulation of EZH2 has been implicated in various malignancies, including CRC, highlighting its role in promoting tumor progression, metastasis, and chemoresistance." (PMID 40314246, 2025). "EZH2 overactivation, driven by RB1 mutations and subsequent E2F overexpression, leads to the silencing of tumor suppressor genes and the activation of oncogenic signaling pathways." (PMID 41194225, 2025). "For example, EZH2 suppresses T cell infiltration and function, thereby fostering an immunosuppressive tumor microenvironment." (PMID 40018411, 2025). "Hematoxylin and eosin (H&E) staining revealed increased cellular density in tumor samples, while immunohistochemistry confirmed elevated EZH2 protein expression in tumor tissues (74T) relative to benign tissues (74B)." (PMID 40766612, 2025). "Collectively, these results delineate a mechanistic pathway linking intracellular copper levels to tumor cell stemness through the modulation of EZH2 protein stability." (PMID 40719074, 2025).
tumor (continued). "MiR-200c is able to affect the process of EMT by regulating EZH2, which affects the spread of tumor cells by regulating the expression of EMT related genes." (PMID 39944625, 2025). "Our analysis revealed that elevated EZH2 expression was correlated with advanced tumor stages, poor histological grades, and reduced OS rates among patients with HCC." (PMID 41298718, 2025). "As Basheer and colleagues demonstrated, the role of EZH2 is very context-dependent, with it being either a tumor suppressor or an oncogene depending on the stage of disease and depending on which of its targets are being manipulated by its activity." (PMID 40791365, 2025). "They found that miR-506 expression was negatively correlated with EZH2 expression, lymph node invasion, tumor growth, metastasis, and TNM stage." (PMID 41018112, 2025). "Owing to its significant role in tumor initiation and progression, targeting EZH2 has become a crucial therapeutic strategy in the treatment of a variety of cancers." (PMID 41226368, 2025). "Here, using transcriptomic inference from SMARCB1-deficient tumor cells, we nominate the DNA damage repair kinase ATR as a target for rational EZH2 combination epigenetic therapy." (PMID 40794452, 2025). "EZH2-mediated promoter hypermethylation represses FBP1, while FBP1 itself inhibits PRC2 activity through direct interaction with EZH2—a tumor-suppressive feedback loop disrupted by genotoxic agents that stabilize EZH2." (PMID 40253354, 2025). "MELK promotes tumorigenesis and progression via activation of PI3K/Akt/mTOR signaling, stabilization of EZH2, histone methylation, and regulation of the tumor immune microenvironment." (PMID 41278210, 2025). "In other tumor types, EZH2 has been shown to regulate key downstream targets to promote and expand the CSC population." (PMID 39789291, 2025). "EZH2 inhibitors have shown that reverse gene silencing suppresses tumor growth and potentially reprograms the immune TME in an OS animal model and cell lines, by reducing the number of immunosuppressive TAMs and Tregs and restoring CXCL9 and CXCL10 expression." (PMID 40868849, 2025). "EZH2 also regulates tumor heterogeneity, promotes Enz resistance, and mediates epigenetic reprogramming to promote secondary metastasis from bones to other organs." (PMID 38566211, 2024). "To date, two kinds of EZH2 inhibitors have been investigated in clinical research for the treatment of drug-resistant tumours." (PMID 38644473, 2024). "After 14 days of treatment, tumors treated with EPZ-6438 alone had not increased in volume, and combination treated tumors grew initially, but began to regress at day 9, and ended with slightly lower tumor volumes than EZH2 inhibition alone." (PMID 38265267, 2024). "Single-cell RNA sequencing and immune cell profiling demonstrated phenotypic changes toward more tumor suppressive phenotypes in EZH2 inhibitor–treated tumors." (PMID 38265267, 2024). "Promoting the transcription of EZH2 or inhibiting the degradation of EZH2 can aggravate the proliferation and metastasis of tumor cells." (PMID 39043634, 2024). "In mice, EZH2 inhibition increases the activity of NK cells and T-cells within the tumor microenvironment, leading to improved overall survival." (PMID 38914477, 2024). "In the EZH2 single agent–treated mice, tumor cells showed higher levels of H2-KdDd, which were reduced in the combination treated tumors potentially through targeting and clearance of MHC-high cells." (PMID 38265267, 2024). "We performed RNA-seq in a total of 28 cases in order to collectively compare our EZH2-mutant tumor samples to their EZH2-WT counterparts and detected 211 differentially expressed genes (DEGs)." (PMID 38658543, 2024).
tumor (continued). "EZH2 expression has been examined after immunostaining of the tumor tissue with EZH2-antibodies and quantified as extent, intensity, and score." (PMID 40135141, 2024). "Since the effects of H3K27me3 are tissue-, context-, and disease-specific, EZH2 can function as either a tumor suppressor or an oncogene." (PMID 38886296, 2024). "In H3.3-K27M patient-derived pHGG cell lines, the inhibition of EZH2 in microglia is able to decrease tumor growth and migration." (PMID 39202398, 2024). "Thereby, enhancement of EZH2 activity reduces the expression of tumor suppressor genes, which ultimately upregulates oncogenic pathways." (PMID 38836164, 2024). "Within HCC, the roles of EZH2 extend to the inhibition of NK cell-mediated anti-tumor immunity and the promotion of both carcinogenesis and drug resistance." (PMID 39516467, 2024). "After binding to the ligand, PROTACs enter the tumour cell, bind specifically to one end of the EZH2 protein, and recruit ubiquitin E3 ligase at the other end to form a triplet EZH2-PROTAC-E3 ligase complex." (PMID 38644473, 2024). "Dysfunction of the SWI/SNF complex caused by SMARCB1 deficits leads to the release of inhibition of EZH2 activity, which leads to carcinogenesis and tumor growth." (PMID 39398818, 2024). "Further studies are necessary to investigate the effects of EZH2 inhibitors on the tumor microenvironment and their ability to enhance immunotherapy including immune checkpoint blockade in SMARCB1-deficient tumors." (PMID 39472584, 2024). "Both downregulation of MELK and EZH2 contributed to enhancing the weight and volume of subcutaneous tumours in nude mice." (PMID 38652219, 2024). "The combined use of anti-PD1 therapy and EZH2 inhibitors (such as GSK126 or EPZ6438) has also shown significant tumor-suppressive effects in LSCC patients." (PMID 39620228, 2024). "The evaluation of EZH2 regulation on the immune response to tumours needs immune proficient mouse model or humanized immune system mouse models." (PMID 38644473, 2024). "Together, these data highlight a potential role for EZH2 in tumor immunity, making this a critical area to investigate." (PMID 38914477, 2024). "Blocking EZH2 activity in some human cancer cell lines, including GBM cells, inhibits growth, suggesting unchecked EZH2 activity causes H3K27 hypermethylation and tumor-suppressor inhibition." (PMID 38334611, 2024). "Apart from NCAPD3 regulation of STAT3, we also reported before that NCAPD3 upregulated other TFs like MYC and EZH2 to promote tumor progression." (PMID 38561330, 2024). "Mechanistically, HOTAIR upregulated the metabolic enzymes UPP1 by recruiting histone methyltransferase EZH2, thereby increasing the tumor progression." (PMID 38696320, 2024). "In MM cell lines and cell-derived xenograft (CDX) models, EZH2 depletion inhibited MM cell proliferation and tumor growth while sensitizing MM cells to ferroptosis." (PMID 39518098, 2024). "It is uncertain to what extent the elevated EZH2 expression we observed in the tumor tissue is attributable to regulatory compensation mechanisms." (PMID 40135141, 2024). "In the first part of this study, we confirmed the expression and amplification of EZH2 in patient tumor samples and patient-derived cell lines." (PMID 39054369, 2024). "Accumulating data show that EZH2 is involved in some tumor-related biological processes, including cell proliferation, autophagy and apoptosis, metastasis, and immunomodulation." (PMID 39013911, 2024). "The current study indicated that miR‐4448 reduced tumor proliferation, invasion, and metastasis through EZH2‐induced EMT, providing a new perspective for designing future therapeutic strategies against SCLC." (PMID 39400978, 2024). "During the period spanning 2004 to 2013, the co-cited references predominantly centered around topics such as DNA methylation, histone deacetylase inhibitors, immunotherapy, and EZH2, reflecting the initial investigations into tumor epigenetic therapy." (PMID 39329125, 2024).